MIR16-2 (microRNA 16-2)
Synonyms: hsa-mir-16-2; MIRN16-2; mir-16-2; mir-16-3
Gene: MicroRNA gene on chromosome 3 (160,404,745 to 160,404,825, forward strand). Ensembl gene ENSG00000198987.
Gene Ontology:
Biological process: miRNA-mediated post-transcriptional gene silencing
Cellular component: RISC complex
Homologues: Orthologues: chimpanzee ptr-mir-16-2 (99% identical), guinea pig MIR16-2 (98% identical), macaque mml-mir-16-2 (98% identical), mouse Mir16-2 (98% identical), rat Mir16 (96% identical), rabbit MIR16-2 (93% identical), pig ssc-mir-16-1 (89% identical), dog MIR16-2 (77% identical), zebrafish mir16a (68% identical), tropical clawed frog xtr-mir-16b (67% identical). Paralogues in human: MIR195 (59% identical), MIR15B (48% identical), MIR15A (46% identical).
Diseases named in the same sentence as MIR16-2 in open-access papers:
MIR16-2 is named in the same sentence as 1 disease in open-access papers, as found by Europe PMC text mining. Sharing a sentence is not in itself a finding about the gene and the disease. The quoted sentences say what the papers report.
cancer (1 paper, 2025). A tumor composed of atypical neoplastic, often pleomorphic cells that invade other tissues. "The most potent of these variants may be mutations in well-known cancer-related miRNA genes, such as MIR16-2, MIR143, or MIR155, or mutations recurring in specific miRNA genes." (PMID 40867048, 2025).